MIR4758 (microRNA 4758)
Synonyms: hsa-mir-4758
Gene: MicroRNA gene on chromosome 20 (62,332,487 to 62,332,557, reverse strand). Ensembl gene ENSG00000284074.
Diseases named in the same sentence as MIR4758 in open-access papers:
MIR4758 is named in the same sentence as 2 diseases in open-access papers, as found by Europe PMC text mining. Sharing a sentence is not in itself a finding about the gene and the disease.
MIR4758 shares sentences with these, for which no sentence is quoted: colorectal cancer (1 paper); non-small cell lung carcinoma (1).